CADM1 (cell adhesion molecule 1)
Diseases named in the same sentence as CADM1 in open-access papers (continued):
Sharing a sentence is not in itself a finding about the gene and the disease.
ischemia (1 paper, 2019). A hypoperfusion of the BLOOD through an organ or tissue caused by a PATHOLOGIC CONSTRICTION or obstruction of its BLOOD VESSELS, or an absence of BLOOD CIRCULATION. "The expression of αCTF was detectable in association with a reduction in the full-length level, and these changes in CADM1 concentrations were increased under combined conditions (0.5% serum and 15% O2), suggesting that ischemia caused CADM1 shedding in distal tubules." (PMID 31316980, 2019). "We also conducted Western blot analyses of the urine samples to confirm that the urinary CADM1 measured by the ELISA was CADM1-NTF, and used cell culture experiments to determine whether CADM1 shedding was induced in tubular cells by ischemia." (PMID 31316980, 2019). "Urinary CADM1 may subsequently increase when ischemia is relatively severe in the renal cortex." (PMID 31316980, 2019).
kidney cancer (1 paper, 2020). Primary or metastatic malignant neoplasm involving the kidney. "CADM1 is a tumor suppressor in kidney cancer, which suggests that 4.1N may be involved in renal tumorigenesis." (PMID 32760223, 2020).
mastocytosis (1 paper, 2012). A clonal myeloproliferative neoplasm characterized by the proliferation and accumulation of neoplastic mast cells in one or multiple organs or organ systems. "Our data show that CADM1 plays a key role in MC aggregation and survival and, therefore, is likely to contribute to both clonal expansion and aggregation of MCs in advanced mastocytosis." (PMID 22438059, 2012).
melanoma in situ (1 paper, 2019). "Immunohistochemical staining suggested that CADM1 decreases from nevi to melanoma in situ to metastatic melanoma." (PMID 30911007, 2019).
metastatic disease (1 paper, 2019). "While the function of CADM1 in the formation of nevi is unknown, our data suggest CADM1 plays multiple tumor suppressive functions that would likely be selected against as nevi clonally evolve to in situ and metastatic disease." (PMID 30911007, 2019).
metastatic melanoma (1 paper, 2019). A melanoma that has spread from its primary site to another anatomic site. "Thus, CADM1 may represent a new target of RAS-RAF-MEK-ERK1/2 pathway inhibition in metastatic melanoma patients." (PMID 30911007, 2019).
myelodysplastic syndrome (1 paper, 2022). A clonal hematopoietic disorder characterized by dysplasia and ineffective hematopoiesis in one or more of the hematopoietic cell lines. "Furthermore, CADM1 is deleted in a subset of myelodysplastic syndromes." (PMID 36270981, 2022).
myeloma (1 paper, 2022). "We were surprised to find the three proteins that most-distinguished myeloma plasma cells from B-ALL, based on fold-change and p-value, were not canonical markers at all: gamma-glutamyl transferase 1 (GGT1), selectin-P ligand (SELPLG), and cell adhesion molecule 1 (CADM1)." (PMID 35840578, 2022).
neuroendocrine tumor (1 paper, 2022). "Among these, SCGN, CHGA and CADM1 are known neuroendocrine tumor markers, suggesting this proteotype is neuroendocrine-like." (PMID 35383171, 2022).
oropharyngeal tumors (1 paper, 2014). "CADM1 protein expression was reduced in 89% of the oropharyngeal tumors, suggesting that next to epigenetic silencing other nonepigenetically mechanism might account for the reduced expression." (PMID 25065733, 2014).
primary aldosteronism (1 paper, 2025). An endocrine disorder characterized by excessive production of aldosterone by the adrenal glands. "Further interest in this question came from the recent discovery of primary aldosteronism‐associated mutations in CADM1." (PMID 39877942, 2025). "Mutations in CADM1 were recently associated with primary aldosteronism, and the patho‐physiology was suggested to be linked to the proper formation of connexin 43 gap junctions in the ZG." (PMID 39877942, 2025).
primary sclerosing cholangitis (1 paper, 2021). "In patients with IBD + primary sclerosing cholangitis, LSECs expressed a high level of mucosal address in cell adhesion molecule-1, which promoted the adhesion of α4β7+ mucosal lymphocytes with hepatic sinusoid endothelium." (PMID 34336855, 2021).
rectal cancer (1 paper, 2015). A primary or metastatic malignant neoplasm that affects the rectum. "The biomarker signature was comprised of seven proteins (CADM1, LGALS3BP, HYOU1, FN1, VTN, LRG1, and MRC2) (Fig4A) that could predict the localization of rectal tumors especially well (86% of subjects with rectal cancer)." (PMID 26253080, 2015).
signet ring cell carcinoma (1 paper, 2021). A usually aggressive, poorly differentiated invasive adenocarcinoma characterized by the presence of malignant glandular cells in which the nucleus is pressed to one side by the presence of intracytoplasmic mucus. "Furthermore, it has been recently reported that CADM1 might play an important role on peritoneal dissemination of tumor cells of signet ring cell carcinoma through promoting their adhesion to peritoneal cells and their growth in the serosal tissue." (PMID 34257559, 2021).
squamous intraepithelial lesions (1 paper, 2022). "CADM1 methylation was significantly higher in high-grade squamous intraepithelial lesions (HSIL) compared with low-grade (LSIL) (p = 0.005) or normal (p < 0.001) samples with 67.2% correctly identified as HSIL." (PMID 35241698, 2022).
tongue cancer (1 paper, 2022). A malignant neoplasm affecting the tongue. "Related researches showed that failure to up-regulate CADM1 in response to chemotherapeutic drugs may contribute to therapy resistance in AML and CADM1 sensitizes tongue cancer cells to chemotherapy." (PMID 36523593, 2022).
triple-negative breast carcinoma (1 paper, 2021). An invasive breast carcinoma which is negative for expression of estrogen receptor (ER), progesterone receptor (PR), and human epidermal growth factor receptor 2 (HER2). "However, after primary systemic therapy (PST), patients with incomplete remission have low CADM1 levels, which suggests that CADM1 downregulation is associated with low therapeutic effect of PST in triple-negative breast cancer." (PMID 34395444, 2021). "Interestingly, CADM1 expression is upregulated in most triple-negative breast cancer cases." (PMID 34395444, 2021).
type 2 diabetes (1 paper, 2024). "The top suggestive associations in early (POU5F1-whole blood), late (CADM1-breast), and total (TLCD2-subcutaneous adipose) GWG using maternal genotypes have also been tied to related traits, including BMI, BMI-adjusted hip circumference, type 2 diabetes, and waist to hip ratio." (PMID 38854080, 2024).
tumor (163 papers, 2005 to 2026). "CADM1 encodes an immunoglobulin-superfamily cell adhesion molecule involved in epithelial adhesion, immune cell interactions, and tumor suppression in colon and various cancers." (PMID 42123493, 2026). "CADM1 (also known as TSLC1) is a tumor-suppressor gene that encodes an intracellular adhesion protein of the immunoglobulin superfamily." (PMID 35402283, 2022). "The most frequently tested host-genome methylation markers in cervical smears and tumours are cell adhesion molecule 1 (CADM1) and T-lymphocyte maturation-associated protein (MAL)." (PMID 35725812, 2022). "Low CADM1 expression on the tumor was associated with poor differentiation, whereas the Kaplan–Meier curve and log-lank test indicated a favorable prognosis with high CADM1 expression." (PMID 34064472, 2021). "CADM1 was expressed in the marginal region of the tumor, whereas loss of CADM1 expression was observed in unfavorable clinical cases." (PMID 34064472, 2021). "As MMP-2 and MMP-9 are key regulators of extracellular matrix (ECM) degradation and tumor invasion, CADM1 is therefore a metastasis susceptibility gene and is involved in the invasion-metastasis cascade in MM." (PMID 31334110, 2019). "Our study also showed that CADM1/TSLC1 expression was significantly associated with sex and tumor pathological grade, in which CADM1/TSLC1 was more frequently expressed in male patients than in female patients with ESCC." (PMID 26880895, 2016). "Overall, this study identifies a novel mechanism by which CADM1 prevents SqCC progression and suggests that screening tumours for loss of CADM1 expression will help identify those patients most likely to benefit from JAK/STAT targeted chemotherapies." (PMID 27035095, 2016). "Loss of CADM1 protein expression was associated with disease stage, lymph node status, and tumor size in primary BC." (PMID 24833255, 2014). "The observed down-regulation of CADM1 not only in BCBM but also in LN metastases as compared to the primary tumor supports the role of CADM1 as a metastasis susceptibility gene in terms of reducing the metastatic capability." (PMID 24833255, 2014). "This loss or reduction in Cadm1 expression is associated with increased tumor grade, stage, and local invasiveness." (PMID 23028344, 2012). "Inactivation of CADM1, either by promoter hypermethylation or loss of heterozygosity, has been reported in a wide variety of tumor types, thus it has been postulated as a tumor suppressor gene." (PMID 22553910, 2012). "Tumorigenesis was accelerated after irradiation of Cadm1 mice, with the reduced latency in tumor formation suggesting there are genes that collaborate with loss of Cadm1 in tumorigenesis." (PMID 22553910, 2012). "Our insertional mutagenesis screen provides new insights into Cadm1-mediated tumor suppression by identifying genes that co-operate with loss of Cadm1 in lymphomagenesis, in particular those regulating glucocorticoid signaling and cell junctions." (PMID 22553910, 2012). "In this study, we employ a complex genetics screen that exploits the differential heritable metastatic susceptibility observed among strains of inbred mice to identify tumor-autonomous expression of Cadm1 as a germline modifier of metastatic susceptibility." (PMID 23028344, 2012). "Thus, CADM1 is associated with nervous system tumors and can act as an effective indicator of tumor progression." (PMID 34395444, 2021). "In addition, clinical data suggest that membrane colocalization of CADM1 and 4.1R is associated with higher tumor stage, and CADM1-4.1R complex contributes to SCLC malignancy." (PMID 34395444, 2021). "Although the reason remains unclear, the characteristics of tumor origins might be associated with the role of CADM1 in tumor development." (PMID 33419290, 2020).
tumor (continued). "Additionally, the loss of CADM1, a tumor suppressor gene involved in cell–cell interactions and epithelial-like phenotype, can contribute to cancer invasion and metastasis in epithelial-derived cancers by inducing epithelial mesenchymal transition (EMT)." (PMID 29262659, 2017). "The ability of this strategy to both re-identify known metastasis susceptibility genes (e.g., Cadm1) and validate novel tumor progression genes (e.g., Pvrl1, Zbtb16) is consistent with this hypothesis." (PMID 27074153, 2016). "And the positive rate of CADM1/TSLC1 was associated with the tumor pathological grade (p < 0.01), with grade I, grade II, and grade III being 86.5% (77/89), 89.0% (145/163), and 34.1% (14/41), respectively, and the difference was statistically significant (p < 0.01)." (PMID 26880895, 2016). "However, more than a 30-fold upregulation of CADM1 in HTLV-1-associated ATL tumor cells was critical for tumor cell progression and invasion." (PMID 25774694, 2015). "Consistent with the membranous staining, a statistically significant association between loss of CADM1 in the nucleus and more aggressive or advanced tumor stage and size, as well as for the hormone receptor status and the course of disease (p < 0.05) was found (only assessed on TMA I)." (PMID 24833255, 2014). "To gain mechanistic insights into how loss of Cadm1 results in increased tumorigenesis, we performed an insertional mutagenesis screen using the Sleeping Beauty (SB) transposon in Cadm1 mice to identify genes that co-operate with loss of Cadm1 in tumor formation." (PMID 22553910, 2012). "Thus we have shown that CADM1 is a bona fide tumor suppressor gene, and loss of Cadm1 results in an increased tumor incidence." (PMID 22553910, 2012). "However, the mechanism underlying tumor suppression by CADM1 remains to be fully elucidated." (PMID 25159494, 2014). "Cadm1 encodes a trans-membrane glycoprotein adhesion molecule of the immunoglobulin superfamily for which a number of disparate functions have been reported including; tumor suppression, synapse development, behavioral regulation, T cell adhesion, mast cell interactions, and spermatogenesis." (PMID 22876197, 2012). "Thus loss or reduction in Cadm1 expression may contribute to the final step of cancer immunoediting: tumor cell “escape” from detection by the immune system." (PMID 23028344, 2012). "Cell adhesion molecule 1 (CADM1) is a member of the immunoglobulin superfamily, and increased CADM1 expression can inhibit tumor progression by suppressing the PI3K-AKT signaling pathway." (PMID 41507145, 2026). "For example, CADM1 enhances immune-mediated clearance of tumor cells and suppresses tumor invasiveness by modulating cell–cell adhesion and natural killer (NK) cell-mediated cytotoxicity." (PMID 41409250, 2025). "CADM1 (cell adhesion molecule 1) is a multifunctional cell adhesion molecule that has been recognized as a tumor suppressor gene." (PMID 41026459, 2025). "NK cell-mediated rejection of CADM1-expressing tumours is also influenced by the CRTAM gene in vivo, thus regulating the activation of various T-cell subtypes." (PMID 40759637, 2025). "Nevertheless, evidences had stated clearly that the loss of CADM1 expression is interrelated with histological grades and cancer prognosis, the lower the CADM1, the stronger the tumor aggressiveness and the worse the prognosis." (PMID 37814227, 2023). "As a tumor regulator, the cell adhesion molecule CADM1 is involved in cell adhesion and signal transduction, and produces a certain effect on the occurrence and development of tumors." (PMID 37814227, 2023). "miR-148a exerts its oncogenic influence by directly targeting CADM1 (cell adhesion molecule 1), which is a tumor suppressor gene that inhibits cell motility and tumor proliferation." (PMID 37371047, 2023). "The mechanism of action of this miRNA is based on downregulation of the cell adhesion molecule 1 (CADM1) that functions as a tumor suppressor." (PMID 36980974, 2023).
tumor (continued). "We selected four markers that were differentially expressed in normal and tumor human lung tissues: CADM1, KRT16, MMP1, and NAPSA." (PMID 38067281, 2023). "From a macro-perspective, higher clinical presentations of CADM1 have been correlated with tumor size and staging." (PMID 37970212, 2023). "Previous studies have shown that decreased expression of CADM1 is correlated with tumor aggressiveness and progression in numerous types of cancer." (PMID 35477343, 2022). "Reportedly, some proteases, such as ADAM10 and γ-secretase, induce the membrane-proximal cleavage of CADM1, called shedding, that results in MF-CADM1 formation on tumor cells." (PMID 35805896, 2022). "Together, our studies corroborate a role for CADM1 as a tumor suppressor, regulating proliferation and keeping tumorgenicity at bay." (PMID 36316307, 2022). "In a retrospective analysis of 88 patients diagnosed with cSCC at our institution between January 2006 and December 2016, the degree of CADM1 expression in tumor cells was evaluated by immunostaining." (PMID 34064472, 2021). "In this sense, upregulation of CADM1 along with downregulation of E-cadherin on tumor cells undergoing EMT are major factors that contribute to NK cell-mediated immunosurveillance of metastasis." (PMID 34858978, 2021). "Knockdown of CADM1 significantly enhances progression, tumor cell proliferation, and colony formation, while inhibiting apoptosis." (PMID 34395444, 2021). "Clinically, high CADM1 expression is correlated with disease stage, lymph node status, and tumor size, which results in a higher cumulative survival index." (PMID 34395444, 2021). "CADM1 can achieve tumor suppression through 4.1 binding motif and 4.1B/DAL1 binding, or participate in cbp-dependent c-Src regulation, thereby inhibiting tumorigenicity in nude mice." (PMID 34395444, 2021). "Cell adhesion molecule 1 (CADM1), one of adhesion molecules, is a well-known tumor suppressor gene in a variety of human cancers." (PMID 34574062, 2021). "CADM1 was frequently reported as a tumor suppressor and mostly was abrogated in various cancer types." (PMID 34497766, 2021). "First, to examine the impact of CADM1 on the survival of cSCC patients, the survival rates for the tumor were evaluated using the Kaplan–Meier method." (PMID 34064472, 2021). "In view of these findings, we believe that CADM1 as a biomarker will play an increasingly important role in tumor diagnosis and prognosis monitoring." (PMID 34395444, 2021). "CADM1 protein overexpression suppressed the proliferative ability, decreased the invasive ability, and triggered the apoptosis of tumor cells in vitro." (PMID 34105305, 2021). "Cell adhesion molecule 1 (CADM1) as a tumor-suppressor, can down-regulate expression of c-Src in suppressing colon tumorigenesis." (PMID 34943856, 2021). "CADM1 expression reflects a tumor-side factor, whereas the clinical stage is influenced by both the tumor and host factors." (PMID 34064472, 2021). "While acting as a tumor suppressor, CADM1 promotes cell apoptosis by regulating apoptosis-related proteins, caspase, and Bax, thereby inhibiting the malignant proliferation of tumors." (PMID 34395444, 2021). "In HCC, the lncRNA DLX6-AS1 is involved in the STAT3 signaling pathway, which regulates the expression of CADM1 and participates in tumor progression." (PMID 34395444, 2021). "Based on the studies discussed herein, CADM1 is involved in the regulation of tumor formation by participating in the EMT, Hippo, AKT, MAPK, and other related signaling pathways." (PMID 34395444, 2021). "CADM1 functions along with a variety of regulatory molecules and signaling pathways to regulate tumor proliferation, apoptosis, metastasis, and other functions in multiple organ systems." (PMID 34395444, 2021). "Both miR-21 and miR-155 can promote cancer aggressiveness via commonly targeting a tumor-suppressive gene such as cell adhesion molecule 1 (CADM1)." (PMID 33066509, 2020).